TIMM8A (translocase of inner mitochondrial membrane 8A)
Diseases named in the same sentence as TIMM8A in open-access papers (continued):
Sharing a sentence is not in itself a finding about the gene and the disease.
auditory neuropathy (4 papers, 2019 to 2022). A hearing disorder characterized by impaired transmission of signals through the auditory nerve, resulting in mild to severe hearing loss and poor speech perception. "Previous research has established that the proportion of TIMM8A mutation in the population with auditory neuropathy was 1.8 %, and the deafness-myotension disorder-optic neuropathy (DDON) syndrome was caused by the unassembled DDP1/TIMM8a-TIMM13 complex in mitochondria." (PMID 36207751, 2022). "This indicated that TIMM8A might have the same pathogenic pathway in DDON, auditory neuropathy, BRCA, and UCEC." (PMID 36207751, 2022). "Massive parallel sequencing using an auditory neuropathy panel and buccal cells of the patient uncovered an A>T change in the initiation codon, which can in theory alter both translation initiation and possibly TIMM8A transcription." (PMID 31903733, 2020). "Furthermore, we found another two TIMM8A variations, the deletion c.133_135delGAG and a copy number variation (CNV) including the TIMM8A gene, in two independent case, when we performed NGS on an auditory neuropathy population." (PMID 30634948, 2019).
X-linked agammaglobulinemia (2 papers, 2012 to 2019). X-linked agammaglobulinemia (XLA) is a clinically variable form of isolated agammaglobulinemia, an inherited immunodeficiency disorder (see this term), and is characterized in affected males by recurrent bacterial infections during infancy. "The DDON syndrome is linked to mutation in TIMM8A or to a deletion at Xq22, also causing X-linked agammaglobulinemia due to the disruption of the BTK gene located telomeric to TIMM8A." (PMID 22776096, 2012).
ductal carcinoma (1 paper, 2022). "Moreover, the lobular epithelial (N-Lobular) tissues exhibited significantly lower expression of TIMM8A relative to ductal carcinoma." (PMID 35501914, 2022).
lung carcinoma (1 paper, 2025). "The analysis revealed that lung cancer patients with high expression of either TIMM8A or TIMM13 exhibited a worse overall survival rate." (PMID 40918471, 2025). "Our research demonstrates significant overexpression of both TIMM8A and TIMM13 in lung cancer tissues, correlating with aggressive clinical pathological features and poor prognosis." (PMID 40918471, 2025).
neuropathy (1 paper, 2023). A disorder affecting the nervous system that manifests with pain, tingling, numbness, and/or muscle weakness. "TIMM8A and AIFM1 mutation has been identified as potential factors contributing to the development of postsynaptic neuropathy." (PMID 38027523, 2023).
otitis media (1 paper, 2020). Inflammation of the anatomical structures of the middle ear, which is most often caused by an infectious process. "Second, to those with the DDON phenotype accompanying recurrent otitis media, sinusitis, or/and pneumonia, we recommend assessing their BTK expression level and investigating whether they belong to CGS involving the BTK and TIMM8A genes." (PMID 33013854, 2020).
ovarian carcinoma (1 paper, 2022). A malignant neoplasm originating from the surface ovarian epithelium. "TIMM8A has been linked to the growth of SKOV3/DDP ovarian cancer cell line subcutaneous xenografts." (PMID 36248992, 2022). "It has been reported that Mutations in the TIMM8A gene lead to Mohr-Tranebjrg Syndrome (MTS), and TIMM8A is related to the proliferation of ovarian cancer cell line SKOV3/DDP subcutaneous xenografts." (PMID 36248992, 2022).
Parkinson disease (1 paper, 2022). A progressive degenerative disorder of the central nervous system characterized by loss of dopamine producing neurons in the substantia nigra and the presence of Lewy bodies in the substantia nigra and locus coeruleus. "In KEGG analysis, 6 pathways including ribosome, oxidative phosphorylation, spliceosome, proteasome, Parkinson disease, and DNA replication were associated with the functions of TIMM8A mutations in UCEC." (PMID 36207751, 2022).
prostate carcinoma (1 paper, 2023). A carcinoma that arises from epithelial cells of the prostate gland. "Two KLF5K369Q-upregulated and NTZ-downregulated genes, MYBL2 and TIMM8A, were upregulated in human prostate cancer, and the upregulation was associated with worse patient survival." (PMID 36810084, 2023). "For example, two Ac-KLF5-upregulated and NTZ-downregulated genes, MYBL2 and TIMM8A, were upregulated in human prostate cancer." (PMID 36810084, 2023). "In the GSE21034 dataset, expression levels of both MYBL2 and TIMM8A were available in primary tumors, visceral metastases, and bone metastases of prostate cancer." (PMID 36810084, 2023).
cancer (6 papers, 2022 to 2024). A tumor composed of atypical neoplastic, often pleomorphic cells that invade other tissues. "In this study, for the first time, we comprehensively analyzed the expression of TIMM8A and its association with the prognosis of cancer patients using databases such as Ualcan, PrognoScan, Human Protein Atlas, and Kaplan-Meier plotter." (PMID 36207751, 2022). "This might lead to differences in the degree of CTL infiltration associated with TIMM8A in the two cancers and might be related to the mechanisms of immune evasion of BRCA and UCEC." (PMID 36207751, 2022). "To explore the mechanism underlying the effect of TIMM8A on BRCA and UCEC survival, we investigated whether TIMM8A expression was associated with immune infiltration levels in these two cancers with the TIMER database." (PMID 36207751, 2022). "Further, SELENOW is expressed in the brain and is implicated in EGF signaling and redox regulation, while TIMM8A is involved in mitochondrial function with its role in cancer currently evolving." (PMID 39123468, 2024). "Pan-cancer analysis was firstly performed for TIMM8A’s expression and prognosis by Oncomine database." (PMID 35501914, 2022). "Taken together, for the first time, our pan-cancer analyses of TIMM8A indicated statistical correlations of TIMM8A expression with clinical prognosis in BRCA and UCEC." (PMID 36207751, 2022). "We first analyzed the transcriptional levels of TIMM8A in 20 types of human cancer with those in normal samples using Oncomine databases." (PMID 35501914, 2022). "In UCEC, the expression level of TIMM8A increased following the cancer stages (UCEC: stage 1 median = 8.089, stage 2 median = 9.817, stage 3 median = 10.024, stage 4 median = 10.095)." (PMID 36207751, 2022). "In this study, we observed a statistically significant difference in the expression levels of TIMM8A between 15 cancers and corresponding normal tissues using the RNA-seq data of various malignant tumors in the TIMER database." (PMID 36207751, 2022). "This study illustrated that TIMM8A was abnormally expressed in a variety of malignant tumors, and significantly affected the prognosis of BRCA and UCEC for the first time." (PMID 36207751, 2022). "The results suggest that compared with normal tissues, TIMM8A was significantly up-regulated in 16 of 33 cancers." (PMID 36248992, 2022). "We investigated the link between the degree of DNA methylation in TIMM8A and the prognosis of cancer patients." (PMID 36248992, 2022). "It indicated that the expression of TIMM8A mRNA was abnormal in different cancer types." (PMID 36248992, 2022). "Therefore, we firstly performed a pan-cancer analysis to investigate the expression of TIMM8A in different cancer types." (PMID 35501914, 2022). "While in UCEC, the expression of TIMM8A increased following the cancer stages." (PMID 36207751, 2022). "TIMM8A expression exhibited an excellent capacity to differentiate cancer and normal tissues, suggesting that it could be took as a potentially beneficial diagnostic and prognostic marker for BC." (PMID 36248992, 2022). "Based on previous findings, we speculated that abnormal expression of TIMM8A in cancer might also affect the function of immune cells by affecting mitochondria, thereby affecting the development and prognosis of cancer." (PMID 36207751, 2022). "Our results suggested that myeloid-derived suppressor cells (MDSC) and tumor-associated M2 macrophages (TAM M2) might be important factors in immune evasion through T cell rejection in both cancers, and considered TIMM8A as a biomarker to predict the efficacy of this therapy in BRCA and UCEC." (PMID 36207751, 2022). "Up to date, a large number of studies have uncovered multiple genes can serve as biomarkers for immunotherapy response in BrCa or other cancer types, such as CCDC69, TIMM8A, and ACE2." (PMID 36583022, 2022).
cancer (continued). "And found that the expression of TIMM8A in BRCA and UCEC substantially increased following the cancer stages, which contributed to illustrate the value of TIMM8A as a prognostic biomarker in BRCA and UCEC." (PMID 36207751, 2022). "While the biological functions of TIMM family have gradually advanced, the potential role of TIMM8A has never been investigated in cancer." (PMID 35501914, 2022). "We further explored the effect of TIMM8A on the level of immune infiltration in BRCA and UCEC and preliminarily speculated that TIMM8A affected immune infiltration in BRCA and UCEC by affecting mitophagy, thereby leading to the poor prognosis of these two cancers." (PMID 36207751, 2022). "However, no study has evaluated functional role of TIMM8A in cancer." (PMID 35501914, 2022).
tumor (6 papers, 2009 to 2025). "Correlation analysis showed that TIMM8A expression was associated with tumor immune cell infiltration." (PMID 36248992, 2022). "The findings in this report elucidate the important role of TIMM8A in BRCA and UCEC, provide potential relationships and underlying mechanisms between TIMM8A and tumor-immune interactions, and provide insights into the use of anti-PD-L1 therapy in BRCA and UCEC." (PMID 36207751, 2022). "TIMM8A is involved in tumor progression by regulating mitochondrial function and cellular metabolic reprogramming, exerting its effects through modulating reactive oxygen species (ROS) levels and mitochondrial respiration." (PMID 41409294, 2025). "TIMM8A expression was analyzed via the Tumor Immune Estimation Resource (TIMER) site and UALCAN database." (PMID 36207751, 2022). "In addition, the correlation between TIMM8A and immune infiltration was examined by Tumor Immune Estimation Resource (TIMER) and Tumor Immune System Interaction Database (TISIDB)." (PMID 36248992, 2022). "In addition, we investigated the association of TIMM8A with tumor-infiltrating immune cells in BRCA and UCEC through the Tumor Immunity Estimation Resource (TIMER) and TIDE databases." (PMID 36207751, 2022). "In addition, the gene expression profile of TIMM8A between tumor and normal breast tissues was obtained using the GEPIA database." (PMID 35501914, 2022).
neurodegenerative disease (4 papers, 2019 to 2023). A disorder of the central nervous system characterized by gradual and progressive loss of neural tissue and neurologic function. "In addition, it has been reported that the neurodegenerative disease Mohr–Tranebjaerg syndrome is caused by mutation of Timm8a, which forms a complex with Timm13, indicating that Timm13 is related to neurodegenerative diseases." (PMID 36899394, 2023). "However, it is known that the neurodegenerative disease, Mohr–Tranebjaerg syndrome, occurs due to a mutation in TIMM8A, which acts as a complex with TIMM13, suggesting its association with neurodegenerative disease." (PMID 34685681, 2021).
TIMM8A also shares sentences with these, for which no sentence is quoted: autoimmune disease (2 papers); optic atrophy (2); osteosarcoma (2); Allergy (1); Alport syndrome (1); Alström syndrome (1); asthma (1); Ataxia (1); atrial fibrillation (1); autoimmune disorders (1); bladder urothelial carcinoma (1); Cholestatic liver disease (1); cognitive decline (1); colon adenocarcinoma (1); cortical blindness (1); cutaneous melanoma (1); elliptocytosis (1); endocervical carcinoma (1); endometrial carcinoma (1); esophageal carcinoma (1); head and neck cancer (1); heart failure (1); inflammatory bowel disease (1); ischemic heart disease (1); kidney chromophobe (1); lung adenocarcinoma (1); lung squamous cell carcinoma (1); melanoma (1); mental retardation (1); Paranoia (1).
A further 11 diseases each share a sentence with TIMM8A in 1 paper.